CD3E (CD3 epsilon subunit of T-cell receptor complex)
Diseases named in the same sentence as CD3E in open-access papers (continued):
Sharing a sentence is not in itself a finding about the gene and the disease.
enteritis (1 paper, 2022). Inflammation of the small intestine. "We also observed that, when enteritis was induced in the small intestine by repeated injections of an anti-CD3ε agonistic antibody,36,37Nfkbizfl/flVil1-Cre mice lost more weight than control mice, which is indicative of increased inflammation." (PMID 35999460, 2022).
food allergy (1 paper, 2021). Gastrointestinal disturbances, skin eruptions, or shock due to allergic reactions to allergens in food. "Here, our results show the association between DNAm levels with food allergy for CXCL12, CCR7, RUNX1, and CD3E." (PMID 33571165, 2021).
Glomerular sclerosis (1 paper, 2025). Accumulation of scar tissue within the glomerulus. "The areas stained for glomerulus and tubular damage (tubular atrophy, interstitial inflammation, glomerular sclerosis, interstitial fibrosis), CD3e, CD68, and COL1α1 were significantly reduced after GQDs pre‐treatment." (PMID 39739624, 2025).
Graves disease (1 paper, 2022). Graves' disease is an autoimmune disorder that leads to overactivity of the thyroid gland (hyperthyroidism).It is caused by an abnormal immune system response that causes the thyroid gland to produce too much thyroid hormones. "Epigenetic changes in genes involved in T cell signaling were found in Graves' disease patients including CD3E gene, as well as downregulation of other CDE genes." (PMID 35237542, 2022).
heart failure (1 paper, 2021). Inability of the heart to pump blood at an adequate rate to meet tissue metabolic requirements. "To determine the effects of T cells on heart failure, we performed TAC on T cell-deficient CD3ε-/- mice as a model for heart failure." (PMID 34745139, 2021). "Furthermore, CD3ε-/- mice had lower mRNA levels of Nppb, which encodes brain natriuretic peptide (BNP), a marker of heart failure, as well as lower levels of Col1a1, a fibrosis marker, compared to WT mice." (PMID 34745139, 2021).
ischemia (1 paper, 2018). A hypoperfusion of the BLOOD through an organ or tissue caused by a PATHOLOGIC CONSTRICTION or obstruction of its BLOOD VESSELS, or an absence of BLOOD CIRCULATION. "There was also a significant increase in both CD3e (T-lymphocyte) and B220 (B-lymphocyte) immunoreactivity between four and eight weeks following ischemia in the brain, with no apparent increase in collagen deposition in the brain infarcts between four and eight weeks following ischemia." (PMID 30417081, 2018).
kidney transplant (1 paper, 2017). A surgical procedure in which one or both kidneys from a donor are implanted into a recipient. "Urinary mRNA analysis with three-gene set (18S rRNA, CD3ε, and IP-10) has been suggested as a non-invasive biomarker of acute rejection (AR) in kidney transplant recipients using quantitative real-time PCR (qPCR)." (PMID 28654700, 2017).
Klebsiella Infections (1 paper, 2012). Infections with bacteria of the genus KLEBSIELLA. "Although lung-resident innate-like T cells did not constitutively express IL-17A as assessed by the hNGFR reporter, γδ T cells, iNKT cells and other CD3ε+ cells expressed hNGFR within 24 hr after Klebsiella infection or 8 hr after administration of IL-1β and/or IL-23." (PMID 22768117, 2012).
leprosy (1 paper, 2019). Leprosy is a chronic infectious disease affecting primarily the skin and peripheral nervous system. "When comparing leprosy patients to HHC, 16 genes showed significantly different expression for leprosy patients (increased: FCGR1A, IL6, IL15, LRKK2, MBP, MSR1, PACRGv1, TLR1, TLR4; decreased: CAMTA, CD3E, CTLA4, CXCL13, GATA3, LAG3, TFGB)." (PMID 31784594, 2019).
metastatic tumor (1 paper, 2021). "This is consistent with the gene expression of CD3E which also is unchanged between the primary and recurrent/metastatic tumor." (PMID 33796222, 2021).
Myalgia (1 paper, 2023). "The T-cell marker gene CD3E was associated with myalgia and chills in our analysis." (PMID 38022684, 2023). "While no direct association between CD3E gene and myalgia has been found, there is a strong indication that T cells play a key role not only in the induction but also in the suppression of pain." (PMID 38022684, 2023).
Mycobacterium infection (1 paper, 2021). Infections with bacteria of the genus Mycobacterium. "The role of the remaining 7 genes (CD2, CD6, CD247, ZAP70, CD3D, SH2D1A, and CD3E) in T-cell signaling and modulation of host immune responses in mycobacterium infections is also supported." (PMID 35198572, 2021).
Omenn syndrome (1 paper, 2020). An inflammatory condition characterized by erythroderma, desquamation, alopecia, chronic diarrhea, failure to thrive, lymphadenopathy, and hepatosplenomegaly, associated with severe combined immunodeficiency (SCID). "SCID patients had disease-causing mutations in RAG1 or RAG2 (n = 4, two of them presented with Omenn syndrome), IL2RG (n = 4, one of them with confirmed maternal engraftment), NHEJ1 (n = 1), CD3E (n = 1), ADA (n = 1), JAK3 (n = 3, two of them with maternal engraftment) and DCLRE1C (n = 1)." (PMID 32265901, 2020).
Opportunistic infection (1 paper, 2019). An infection that is caused by a pathogen that would generally not be able to cause an infection in a host with a normal immune system. "Mutations in CD3δ (CD3D), CD3ε (CD3E), and CD3ζ (CD247) cause the T-B+NK+ SCID phenotype, resulting in profound lymphocyte impairment and increased susceptibility to opportunistic infections, in need of rescue by HSCT." (PMID 31921117, 2019).
Pleural effusion (1 paper, 2012). The presence of an excessive amount of fluid in the pleural cavity. "A deficiency in CD3ε has been reported by our group in pleural effusion CD8+ T-cells from lung cancer patients." (PMID 23118782, 2012).
renal cell carcinoma (1 paper, 2018). "VEGFA, KDR, LYN, CD3E and LOX are among those factors that are not identified by DIAMOnD but have a renal cell carcinoma associated literature support." (PMID 29861861, 2018).
rheumatoid arthritis (1 paper, 2020). A chronic, systemic autoimmune disorder characterized by inflammation in the synovial membranes and articular surfaces. "While some authors mention a concomitant diminished CD3ε and TCRζ expression in rheumatoid arthritis, in response to TNF, in murine models of cancer, or in inflamed tissues, some others do not." (PMID 33354577, 2020).
steatosis (1 paper, 2013). Increased lipid within the cytoplasm of cells. "High fat diet induced steatosis resulted in an overall increase in the CD45/CD11b positive myeloid cell population and the CD45/CD3e positive lymphocytic population." (PMID 24039859, 2013).
T cell deficiency (1 paper, 2020). "T cell deficiency in Cd3e−/− SD rats had dramatic reduction in liver accumulation of CD11b+ myeloid cells and B lymphocytes." (PMID 33347431, 2020).
T-cell leukemia (1 paper, 2021). A malignant disease of the T-lymphocytes in the bone marrow, thymus, and/or blood. "To confirm that fucoidan binds TCR/CD3 on the T cell surface, we stably overexpressed RFP (red fluorescent protein) labeled human CD3E, a major component of the TCR/CD3 complex, in Jurkat T cell leukemia cells exhibiting higher transfection efficiencies than primary T cells." (PMID 34434936, 2021).
Thrombocytopenia (1 paper, 2024). A reduction in the number of circulating thrombocytes. "CD3E levels were found to be reduced in patients with SCID, and those of Rab27B and platelet-related proteins were low in patients with WAS, likely reflecting thrombocytopenia and T cell lymphopenia, respectively, in these two IEIs." (PMID 39453496, 2024).
Wiskott-Aldrich syndrome (1 paper, 2020). Wiskott-Aldrich syndrome (WAS) is a primary immunodeficiency disease characterized by microthrombocytopenia, eczema, infections and an increased risk for autoimmune manifestations and malignancies. "We have previously shown that an MS-based approach for the quantification of signature peptides for BTK, WASP, and a T-Cell marker CD3ε from tryptic digests of PBMCs can be used to screen X-linked agammaglobulinemia (XLA), Wiskott-Aldrich Syndrome (WAS), and SCID, respectively." (PMID 32296420, 2020).
tumor (278 papers, 2007 to 2026). "Lower CD3-ε expression within the tumor and the surrounding stroma is associated with BE progression to EAC." (PMID 38781019, 2024). "They generally target the CD3ε subunit of the T-cell receptor and a tumor-associated or tumor-specific antigen." (PMID 39091493, 2024). "TFAB002s bind to both CD20-expressing tumor cells and CD3ε-expressing T cells, causing crosslinking between T cells and tumor cells, which leads to T-cell activation, tumor cell lysis, and subsequent secretion of cytokines." (PMID 39321199, 2024). "In general, bispecific antibodies combine a tumor binding domain, directed to a tumor associated antigen, with a T cell recruitment domain, most often binding to CD3ε." (PMID 36685546, 2022). "T cell engager (TCE) antibodies have emerged as promising cancer therapeutics that link cytotoxic T-cells to tumor cells by simultaneously binding to CD3E on T-cells and to a tumor-associated antigen (TAA) expressed by tumor cells." (PMID 36291540, 2022). "Then, we calculated the relationship between the abundance of tumor infiltrating lymphocytes and the expression, copy number, methylation, or mutation of CD3E in LGG." (PMID 34557404, 2021). "Correlation analysis indicated that CD4 and CD3E expressions were significantly associated with each other in the tumor tissues, suggesting the presence of tumor-infiltrating CD4+ T cells." (PMID 33968044, 2021). "Given the strong association between CD3E and the DC gene signature, we sought to determine the prognostic role of tumor-infiltrating DCs in NB patients." (PMID 33239635, 2020). "Typically the T-cell-receptor–associated CD3ε component on T cells is engaged with one arm of the BsAb, whereas the other arm engages with a tumor-specific HER2 antigen." (PMID 28827777, 2017). "Down-regulation of CD3ε hinders immunosurveillance and has been associated with T cell apoptosis which helps facilitate the role of tumor immune evasion." (PMID 26497558, 2015). "However, when we compared the size of the analyzed tumors and theirs Cd3e mRNA expression level, we observed that lower Cd3e mRNA level is associated with increasing tumor size (p=0.013, Spearman correlation test)." (PMID 37342258, 2023). "Various hCART armed with BiAb directed at CD3ε and various tumor associated antigens were tested for: 1) specific cytotoxicity against solid tumors targets; 2) repeated and dual sequential cytotoxicity; 3) survival and cytotoxicity under in vitro hypoxic condition; and 4) cytokine secretion." (PMID 34290709, 2021). "To explore the association between DEX inhibited-tumor growth and accumulation of immune response-related cells, we measured the levels of Cxcl9, Cxcl10, Cd3e, Gzmb, and Ifng which are closely related to the recruitment, presence, and function of Th1 cells and CD8+ T cells in the TME." (PMID 32156004, 2020). "The tumor cells were strongly expressed CD3ε, CD56, TIA-1, granzyme B and EBV-encoded RNAs." (PMID 23773344, 2013). "DuoBody-CD3x5T4 is hypothesized to cross-link CD3ε-expressing T cells with 5T4-expressing tumor cells, thereby inducing T cell–mediated kill of 5T4-expressing tumor cells, associated with T-cell activation, T-cell proliferation, and production of inflammatory mediators and effector molecules." (PMID 36271507, 2022). "Additionally, CD3E is a typical genetic marker associated with tumor-infiltrating lymphocytes." (PMID 34218795, 2021). "For instance, BBεζ CARs, which combine a 4-1BB co-stimulatory domain with CD3ε and ζ chains, exhibit superior anti-tumor activity in leukemia models compared to BBζ CARs by recruiting LCK through the RK motif." (PMID 41601693, 2026). "Our findings suggest that the UMG1/CD3ε-BTCE selectively exerts potent anti-tumor activity against a relevant subset of TCLs." (PMID 41834433, 2026). "Spatiotemporally released BsAbs can bridge B7-H3 on tumor cells with CD3ε on T cells, activating effector functions and driving tumor-specific cytotoxicity." (PMID 41209565, 2025).
tumor (continued). "As illustrated by our bispecific DARPin TCEs, tumor or virus-specific DARPins can readily be combined with any of the CD3ε-specific DARPins to generate potent, targeted immune responses." (PMID 41321628, 2025). "The majority of cPARP1-positive cells were non-tumor cells (e.g., CD3E+, CD11C+, or CD31+), particularly in peritumoral regions, consistent with the short half-lives of activated T cells, neutrophils and other immune cells." (PMID 41473281, 2025). "TCE is a typical application of bsAbs, with one targeting arm of most TCEs designed to bind specifically to selected tumor-associated antigen (TAA) on the surface of tumor cells and the other targeting arm designed to target the CD3ε chain in the TCR complex." (PMID 40510353, 2025). "Research has found that MHC class I molecule presentation positively correlates with the proportion of CD45+CD3e+ T cells and negatively correlates with tumor growth rate." (PMID 40573881, 2025). "These BsAbs simultaneously bind a TAA and CD3ε on T cells, bridging cytotoxic lymphocytes to tumor cells and inducing major histocompatibility complex (MHC)-independent killing." (PMID 41476945, 2025). "Its presence in the tumor's extracellular matrix leads to T cell apoptosis by binding to N-glycosylated sites on CD3ε/δ, aiding in immune evasion." (PMID 40134029, 2025). "B7-H3×CD3 BsAbs operationalize this concept; among them, MGD009 is a prototypical candidate engineered for high-affinity binding to both B7-H3 and CD3ε, thereby promoting immunological synapse formation between T cells and tumor cells." (PMID 41209565, 2025). "The PR group exhibited similar levels of isPLA positivity in tumour-infiltrating macrophages to the PD group, but markedly lower proportions in CD3e and CD8 T cells." (PMID 39939997, 2025). "Since CD3ε plays a key role in T cell activation, the use of bispecific antibodies against CD3ε and tumor-associated antigen (TAA) has been a focus of research in tumor therapy." (PMID 41427134, 2025). "An analysis of gene expression in lymphocytes within the tumor microenvironment co-expressing with the pan-T-cell marker CD3 epsilon subunit (CD3E) in 9601 human tumors from 31 cancer types was reported." (PMID 39941003, 2025). "Bispecific T cell engagers (BiTEs) fall into the second group, independently activating T-cells to drive cytotoxicity, cytokine release, and B-cell activation by targeting both a tumor antigen and CD3e, leading to T-cell-dependent tumor cell destruction." (PMID 40260236, 2025). "In subsequent years, other non-CAR approaches enhanced γδ T cell efficacy, such as inhibiting CD3ε for better tumor killing and using monoclonal antibodies against CTLA-4 and PD-1 to treat melanoma, yielding positive preclinical results." (PMID 40148988, 2025). "Consistent with this, spatial transcriptomic analysis using Xenium showed differential localization of T cells (Cd3d, Cd3e, Cd3g, Cd8a, Cd8b1, and Cd4) within tumor sections of RPR2 and CRPR2 mice." (PMID 41353272, 2025). "In this study, we developed and characterized bispecific T cell engagers by combining two highly specific DARPin molecules to target the tumor-associated HLA-A∗0201/NY-ESO1157-165 complex and CD3ε." (PMID 41321628, 2025). "By bridging IL-13Rα2+ tumor cells and CD3ε on T cells, the BiTE induces T-cell activation (CD69/CD25 upregulation), GZMB release, and production of inflammatory cytokines (IFN-γ, TNF-α), culminating in tumor-specific lysis." (PMID 41209565, 2025). "Cibisatamab is a T-cell bispecific antibody (TCB) that uses a 2-to-1 molecular format to target carcinoembryonic antigen (CEA) expressed on the surface of tumour cells and CD3ε on T cells." (PMID 38750034, 2024). "In vivo studies in a syngeneic mouse model with subcutaneous implantation of RENCA cells showed that OBP-801 treatment increased the percentage of CD45+CD3e+ T cells in tumor-infiltrating lymphocytes." (PMID 39682244, 2024).